RCC2 (regulator of chromosome condensation 2)
Diseases named in the same sentence as RCC2 in open-access papers (continued):
Sharing a sentence is not in itself a finding about the gene and the disease.
glioma (2 papers, 2022 to 2025). A benign or malignant brain and spinal cord tumor that arises from glial cells (astrocytes, oligodendrocytes, ependymal cells). "In addition, RCC2 enhances glucose metabolism through BACH1-dependent transcriptional upregulation of hexokinase II in glioma." (PMID 39908861, 2025). "A previous report suggested that RCC2 can promote glioma cell proliferation and radio-resistance." (PMID 36111134, 2022). "But, the RT-qPCR results showed that five genes (IKBKB, PDIA4, RCC2, RPL4, and TXNIP) were low expressed in glioma cell lines compared to HA." (PMID 36111134, 2022).
leukemia (2 papers, 2022 to 2023). A malignant (clonal) hematologic disorder, involving hematopoietic stem cells and characterized by the presence of primitive or atypical myeloid or lymphoid cells in the bone marrow and the blood. "We investigated whether IGF2BP3 regulates RCC2 expression by modulating its mRNA stability in leukemia cells." (PMID 35217832, 2022).
melanoma (2 papers, 2013 to 2023). A malignant, usually aggressive tumor composed of atypical, neoplastic melanocytes. "For RFS the most significant associations were observed for rs7538876 (RCC2) in patients with superficially spreading melanoma (SSM) (HR = 2.30, p = 0.0002), and rs6088520 in patients with an intermediate tumor thickness (1-4 mm) (HR = 0.61, p = 0.0004)." (PMID 24188633, 2013). "The replication of the eQTL findings from a prior study and the novel meQTL association of rs7538876 with RCC2 found in our analysis, provide a highly promising rationale for the observed association effect with melanoma recurrence." (PMID 24188633, 2013). "The increased expression of RCC2, likely due to aberrant methylation, associated with “early recurrence” allele [A] in our study, adds further support for a putative oncogenic mechanism of this gene, possibly contributing to worse clinical outcomes and melanoma progression." (PMID 24188633, 2013). "RCC2 has also been shown to be involved in tumor invasiveness and metastasis, suggesting a putative role of this gene in melanoma progression." (PMID 24188633, 2013). "To evaluate whether scNanoGPS can robustly detect major cell types in human tumors, we performed scNanoRNAseq on 4 frozen tumors collected from renal cell carcinoma (RCC1, RCC2) and melanoma (MEL1, MEL2) patients." (PMID 37433798, 2023).
non papillary renal cell carcinomas (2 papers, 2006 to 2023). "Among them, RCC2 (renal cell carcinoma 2, at 14q22-ter) is a locus which is lost in sporadic, non papillary renal cell carcinomas and oncocitomas." (PMID 16403231, 2006).
non-small cell lung carcinoma (2 papers, 2018 to 2020). A group of at least three distinct histological types of lung cancer, including non-small cell squamous cell carcinoma, adenocarcinoma, and large cell carcinoma. "In addition, previous studies report that long non-coding RNAs (lncRNAs), ENST00000439577, are associated with expression of RCC2 and promotion of proliferation, invasion, and migration of non-small cell lung cancer (NSCLC)." (PMID 33521058, 2020). "RCC2 expression level was not significantly different among three grades of non-small cell lung cancer (well-, moderately- and poorly differentiated tumors)." (PMID 29321004, 2018).
atherosclerosis (1 paper, 2025). A disease characterized by the build-up of fatty material and calcium deposition in the arterial wall resulting in partial or complete occlusion of the arterial lumen. "We identified 12 lactylation-related genes that are more reliably associated with atherosclerosis: five upregulated genes (LSP1, IKZF1, MNDA, RCC2, and WAS) and seven downregulated genes (CSRP2, PPP1CB, CSRP1, HEXIM1, CALD1, PDLIM1, and RANBP2)." (PMID 40248193, 2025).
breast fibroadenoma (1 paper, 2020). "Western blot analysis was performed to detect RCC2 expression in ER + breast tumor tissues (n = 13) and breast fibroadenoma tissues (n = 7)." (PMID 32565805, 2020). "Following normalization of RCC2 expression to GAPDH expression, there was a significant increase in RCC2 expression in these ER + breast tumor tissues compared with that in breast fibroadenoma tissues (p=0.004)." (PMID 32565805, 2020). "Western blotting and immunohistochemistry detected significantly increased expression of RCC2 in ER + breast tumor tissues compared with breast fibroadenoma samples." (PMID 32565805, 2020).
breast tumor (1 paper, 2020). "In the present study, we performed immunohistochemistry and detected extensive RCC2 expression in ER + breast tumor tissues." (PMID 32565805, 2020). "Their reports were consistent with our finding on the effect of RCC2 expression on breast tumor cell activities." (PMID 32565805, 2020). "The inhibition of RCC2 expression significantly decreased breast tumor growth and IL-6 levels in the tumor-bearing mice." (PMID 32565805, 2020). "Our results not only correspond to the previous observation regarding the stimulatory effect of estrogen on breast tumor cells but also demonstrate that RCC2 expression strengthens the inhibitory effect of estrogen on apoptosis." (PMID 32565805, 2020). "Furthermore, we used the RT2 ProfilerTM PCR Array, a real-time PCR primer assay in a 96-well plate, to investigate the tumorigenic pathway of RCC2 in breast tumors." (PMID 32565805, 2020). "The cells with RCC2 knockdown were injected into nude mice to generate breast tumor-bearing mice." (PMID 32565805, 2020). "In the present study, we analyzed RCC2 expression in breast tumor tissues." (PMID 32565805, 2020). "The present study demonstrated increased expression of RCC2 in ER + breast tumor tissues." (PMID 32565805, 2020). "Western blotting confirmed the increase in RCC2 protein in ER + breast tumor tissues." (PMID 32565805, 2020). "Immunohistochemistry was performed in a panel of breast tumor tissues to localize RCC2 expression." (PMID 32565805, 2020). "Because MCF-7 cells originated from ER + breast tumor tissues, we transfected MCF-7 cells with an anti-RCC2 shRNA lentivirus vector to inhibit RCC2 expression." (PMID 32565805, 2020). "RCC2 expression upregulated IL-6, IGF1, and TWIST1 expression both in animal models and in cultured ER + breast tumor cells." (PMID 32565805, 2020).
cholangiocarcinoma (1 paper, 2022). A carcinoma that arises from the intrahepatic biliary tree (intrahepatic cholangiocarcinoma) or from the junction, or adjacent to the junction, of the right and left hepatic ducts (hilar cholangiocarcinoma). "Our results demonstrated that the highest frequency type of RCC2 alteration occurs in Cholangiocarcinoma, with “deep deletion” as the predominant type (>5%)." (PMID 36441563, 2022).
diffuse large B-cell lymphoma (1 paper, 2022). "In GBM, SARC, LUAD, and LUSC, RCC2 expression was positively related to MSI, while in LGG, KIPAN, HNSC, PAAD, and diffuse large B-cell lymphoma (DLBC), it was negatively related to MSI." (PMID 36441563, 2022).
gynecologic cancer (1 paper, 2020). "Despite limited evidence, RhoB and RhoC as well as other Rho GTPase associated interactions, including melanoma cell adhesion molecule (MCAM) or regulator of chromosome condensation 2 (RCC2), represent biomarkers with potential in gynecologic cancer therapy." (PMID 32443784, 2020).
infertile (1 paper, 2022). "Although the direct function of RCC2 on blastocyst adhesion has not been investigated, comparison of fertile and infertile human receptive phase uterine lavage by proteomics identifies a significantly higher level of RCC2 in the fertile group." (PMID 36589798, 2022).
liver fibrosis (1 paper, 2024). "Based on the ceRNA network, lncRNA TNFRSF10A-DT/has-mir-873–5/RCC2, UBR4, and the AKR7A2 axis may construct a ceRNA network to participate in the progression of liver fibrosis." (PMID 38378545, 2024).
lymph node metastasis (1 paper, 2023). "The expression of RCC2 and its methylation level, its correlation with lymph node metastasis or disease-free survival (DFS) was analyzed using TCGA database." (PMID 38008751, 2023).
ovarian serous cystadenocarcinoma (1 paper, 2022). A malignant serous cystic epithelial neoplasm arising from the ovary. "The total protein expression of RCC2 was considerably elevated in pancreatic adenocarcinoma (PAAD), COAD, ovarian serous cystadenocarcinoma (OV), GBM and BRCA tumors compared to normal tissues." (PMID 36441563, 2022).
pancreatic cancer (1 paper, 2017). "We conclude that overexpression of miR-1247 is responsible for decreasing RCC2 levels by targeting 3′UTR in pancreatic cancer." (PMID 28460450, 2017). "Taken together, our data suggest that CpG island hypermethylation of miR-1247 is responsible for its downregulation in pancreatic cancer, and ectopic expression of miR-1247 functions as a potential tumor suppressor targeting RCC2 in pancreatic cancer cells." (PMID 28460450, 2017). "In our study, we showed that miR-1247 reduced the expression level of RCC2 at both mRNA and protein levels in pancreatic cancer cells." (PMID 28460450, 2017).
pheochromocytoma and paraganglioma (1 paper, 2022). "The clustering heatmap illustrated that RCC2 expression was positively related to immune cells in KICH, KIRP, KIRC, LGG, thyroid carcinoma (THCA), and pheochromocytoma and paraganglioma (PCPG) tumors." (PMID 36441563, 2022).
preeclampsia (1 paper, 2025). Preeclampsia is a hypertensive disorder of pregnancy that is characterized by new-onset hypertension with proteinuria presenting after 20 weeks of gestation, and depending on mild or severe forms may initially present with severe headache, visual disturbances, and hyperreflexia. "Lastly, we found that the SLC9A9, SH2B3, SDC3, RCC2, F13A1, CCL2, and CBLB in macrophages were likely to be correlated with preeclampsia." (PMID 40216654, 2025). "Of all the immune cell-regulated preeclampsia differential genes SLC9A9, SH2B3, SDC3, RCC2, F13A1, CCL2, and CBLB were consistently expressed in two transcriptome datasets, and all were highly expressed in macrophages." (PMID 40216654, 2025).
prostate adenocarcinoma (1 paper, 2025). "IHC analysis of prostate adenocarcinoma samples showed frequent coexpression of CD24 (49%) and RCC2 (82%) with a positive correlation between coexpression of CD24 (49%) and RCC2 (82%)." (PMID 41090358, 2025).
stomach adenocarcinoma (1 paper, 2022). "We also explored that RCC2 mutations were most frequent in stomach adenocarcinoma." (PMID 36441563, 2022).
testicular germ cell tumor (1 paper, 2022). A germ cell tumor arising from the testis. "The RCC2 gene was positively related to cancer-associated fibroblasts (CAFs) in KIRP tumors while was inversely correlated to CAFs in testicular germ cell tumors (TGCT) tumors." (PMID 36441563, 2022).
uroepithelial carcinoma (1 paper, 2022). "In uroepithelial carcinoma, low expression of RCC2 is more likely to produce an immune response to atezolizumab, which facilitates the clinical survival of patients." (PMID 36441563, 2022).
uveal melanoma (1 paper, 2022). A melanoma derived from melanocytes of the uveal tract. "However, RCC2 mRNA expression in COAD, LUSC, STAD, and uveal melanoma (UVM) was negatively correlated with the stage." (PMID 36441563, 2022).
tumor (23 papers, 2013 to 2025). "Concerning RCC2 intensity of expression, a significant association was observed between larger tumor size and strong RCC2 intensity of expression (P=0.010)." (PMID 39118792, 2024). "In our cohort, a strong and high RCC2 expression showed a significant association with the clinicopathological parameters of poor prognostic significance, including large tumor size, frequent mitoses, high Ki-67 status, presence of LVI, and positive Her2neu." (PMID 39118792, 2024). "Different RCC2-associated immune infiltration patterns were exhibited in different tumor-infiltrating immune cells." (PMID 36441563, 2022). "Correlations between RCC2 expression and tumor-infiltrating immune cells, tumor mutation burden (TMB), microsatellite instability (MSI), chemokine and their receptors were analyzed using TCGA, ESTIMATE algorithm, and TISIDB database." (PMID 36441563, 2022). "We discovered that RCC2 was highly expressed in various tumor tissues and was closely associated with cancer prognosis." (PMID 36441563, 2022). "We finally observed that RCC2 expression was significantly associated with immune scores in 21 tumor types and was related to the stromal scores in 23 cancer types." (PMID 36441563, 2022). "Further, RCC2 is implicated in tumor cell proliferation, apoptosis and sensitivity, and poor prognosis of microsatellite stable (MSS) tumors." (PMID 33521058, 2020). "DNMT1 and p-STAT3 (downstream factors of RCC2) are implicated in therapeutic resistance in GBM tumor cells by functioning in an epistatic manner with RCC2." (PMID 33521058, 2020). "Deletion of a single base in the (A) 10 repeat decreases RCC2 expression, whereas RCC2 knockdown causes MSI tumor arrest at the G2-M phase and increased levels of apoptosis." (PMID 33521058, 2020). "However, RCC2 loss promotes random migration and leads to a failure to maintain natural tumor boundaries in colorectal cancer." (PMID 39908861, 2025). "Thus, the association between RCC2 and Rac1 concerning apoptosis depends on more complex factors that ultimately influence the response of tumor cells to drug-induced apoptosis." (PMID 39118792, 2024). "In addition to RCC2 being involved in multiple steps of pro-tumorigenic phenomena, it is associated with tumor metastases." (PMID 33521058, 2020). "Consistent with in vitro results, xenograft tumor proliferation inhibited by RCC2 silencing was restored only by wild‐type RCC2 overexpression." (PMID 40145796, 2025). "Dysregulated RCC2 expression correlates with tumor development, unfavorable prognosis, and resistance to chemotherapy." (PMID 40145796, 2025). "As previous studies have confirmed that RCC2 expression promotes epithelial-mesenchymal transition (EMT) in tumor cells, we assessed the switch of E-cadherin and N-cadherin." (PMID 39908861, 2025). "RCC2 mRNA expression was not only dramatically increased in tumor tissues from TCGA database and our samples but also significantly upregulated in BLca patients who have developed metastasis after surgery." (PMID 38993556, 2024). "There are growing reports on the role of RCC2 in human tumor growth, apoptosis, EMT, and drug resistance." (PMID 38008751, 2023). "We found that tumor size and tumor weight were significantly increased in RCC2 overexpressed mice but decreased to normal levels after inhibiting with Gli1." (PMID 38008751, 2023). "Since the RCC2 was overexpressed in numerous malignancies and was related to the tumor stage, we further explored its prognostic value in pan-cancers." (PMID 36441563, 2022).
tumor (continued). "It is suggested that the RCC2 gene has a critical role of RCC2 gene in regulating tumor immune microenvironment and the formation of CAFs, and the potential mechanism of RCC2 regulation of CAFs needs further study." (PMID 36441563, 2022). "The roles of RCC2 in tumor immune microenvironment remains a new area worthy of further investigation." (PMID 36441563, 2022). "In contrast, only kidney chromophobe (KICH) demonstrated lower RCC2 expression in tumor tissues (p < 0.05)." (PMID 36441563, 2022). "MiR-29c tumor-suppressor in gastric carcinoma targets the 3′ untranslated region (3′UTR) of RCC2, reducing its expression, thus regulating tumor cell proliferation." (PMID 33521058, 2020). "Mice injected with anti-RCC2 shRNA-infected MCF-7 cells showed less tumor growth than did the mice injected with empty vector-infected cells." (PMID 32565805, 2020). "Our results suggest that increased RCC2 expression stimulates tumor growth by upregulating IGF1, TWIST1, and IL-6 expression." (PMID 32565805, 2020). "High expression level of RCC2 is positively correlated with T status of the tumor, lymph node metastasis, advanced clinical stage, and poor overall survival in LUAD patients." (PMID 33521058, 2020). "The ADC value of tumor tissues generated from anti-RCC2 shRNA-infected MCF-7 cells was also significantly higher than that of tumors generated from empty vector-infected tumor cells (p=0.044)." (PMID 32565805, 2020). "The function of RCC2 in tumor development has been studied extensively in recent years due to its involvement in tumor cell migration." (PMID 33521058, 2020). "The increased expression of RCC2 stimulated cell migration and inhibited apoptosis, while inhibiting RCC2 expression reduced tumor growth in an in vivo animal model." (PMID 32565805, 2020). "On the other hand, low expression level of RCC2 aggravates tumor cell metastasis through α5β1-FN-signaling pathway." (PMID 33521058, 2020). "We also established a tumor-bearing mouse as the in vivo model and cell culture as the in vitro model to observe the effect of changed RCC2 expression on tumor growth." (PMID 32565805, 2020). "This study detected decreased IL-6 levels in tumor-bearing mice that were injected with anti-RCC2 siRNA-transfected MCF-7 cells." (PMID 32565805, 2020). "The review summarizes the role of RCC2 in cell cycle, effects of overexpression of RCC2 gene in development of various cancers, such as promotion of tumor cell metastasis, RCC2 molecular features and proteins that interact with RCC2 as a tumor-promoting gene." (PMID 33521058, 2020). "In this review, we explored proteins that interact with RCC2 to modulate tumor development and cancer therapeutic resistance by regulation of cell cycle process through various signaling pathways." (PMID 33521058, 2020). "Expression level of RCC2 protein determines regulation of tumor cell proliferation, invasion, metastasis, and radio-chemotherapeutic resistance." (PMID 33521058, 2020). "In LUAD, RCC2 is associated with EMT and extracellular matrix remodeling, which contributes to tumor metastasis." (PMID 33521058, 2020). "The role of RCC2 in the cell cycle is positively correlated with tumor formation and tumor cell sensitivity to therapies." (PMID 33521058, 2020). "The average tumor volume in mice injected with anti-RCC2 shRCC2-infected or empty vector-infected MCF-7 cells was 198.9 mm3 and 729.2 mm3, respectively (p=0.002)." (PMID 32565805, 2020). "Forced RCC2 expression in tumor cells attenuates sensitivity of tumor cells to spontaneous or Staurosporine (STS)-induced apoptosis." (PMID 33521058, 2020). "MCF-7 cells with shRNA-mediated knockdown of RCC2 expression were injected into nude mice (n = 5) to generate tumor-bearing mice." (PMID 32565805, 2020).